CD55 (CD55 molecule (Cromer blood group))
Diseases named in the same sentence as CD55 in open-access papers (continued):
Sharing a sentence is not in itself a finding about the gene and the disease.
tumor (continued). "Importantly, the naïve T cells that are stimulated in response to CD55 and CD97 binding are shown to produce cells that behave like Tregs, which would promote tumor progression if expressed in the TME." (PMID 31164885, 2019). "We compared the biodistribution and tumor uptake of 177Lu-anti-CD55 to the non-selective 177Lu-IgG antibody." (PMID 29895866, 2018). "As the gold-standard functional CSC assay is limiting dilution tumor initiation in vivo, we injected CD55-silenced and nontargeted control CSCs into immune-compromised mice at 103, 104, and 105 cells/mouse." (PMID 28838952, 2017). "We observed small populations of tumor cells co-stained with HIF-2α and CD55 antibodies." (PMID 27043658, 2016). "On the basis of these data we can establish that CD55 dependently from HIF-2α expression is necessary to support the migratory/invading ability of tumor cells but is not sufficient to promote stem features." (PMID 27043658, 2016). "Indeed, we have found that complement regulatory proteins CD55 and CD59 are significantly downregulated in latently KSHV-infected endothelial cells and in KS spindle tumor cells." (PMID 25254972, 2014). "CD55 acts as a cellular ligand for CD97; strong CD97 expression by tumour cells at the invasive front has been correlated with a higher clinical stage and increased lymph vessel invasion compared to cases with uniform CD97 staining throughout the tumour." (PMID 21339979, 2010). "Ofcourse, the tumor rejection antigens and stage specific antigens have been well characterized on human embryos, but there are many others such as the TEC antigens (TEC1- TEC4), LeX, LeY, CD46, CD55, and CD59." (PMID 16033656, 2005). "In addition, we found that a synergistically enhanced tumor cell-killing effect could be induced by generating an asymmetric bispecific antibody targeting CD20 and CD55, a complement regulatory protein." (PMID 37880350, 2023). "The result manifested that the tumour growth was more effectively inhibited in the combination treatment of CD55‐TMn and Dox, and tumour volume was only 201 mm3 compared with the 1926 mm3 for PBS, the 1546 mm3 for Dox and the 1104 mm3 for CD55‐TMn after treatment for 30 days." (PMID 33251723, 2020). "Although heterogeneous relative to tumor type, complement proteins expressed by malignant cells are variable; in general, tumor cells express low C8 and C9 but highly express C3 and the regulators factor H, factor I and especially the membrane regulators CD46, CD55 and CD59." (PMID 33147799, 2020). "Additionally, cancer cells may overexpress several surface receptors, including CD46, ICAM-1 (CD54), DAF (CD55), CD155 and integrins, which enable OVs to enter tumor cells in the TME." (PMID 32411132, 2020). "Interestingly, in this instance it appears that rather than CD55 being a marker of tumor cells, CD55 expression instead lends to a microenvironment that is favorable for a malignant transformation." (PMID 31164885, 2019). "The 177Lu-anti-CD55 antibody was primarily retained in tumor tissue rather than normal tissue." (PMID 29895866, 2018). "However, we did not exclude the possibility that 177Lu-anti-CD55 inhibited metastasis by decreasing tumor cell viability." (PMID 29895866, 2018). "The expression of CD55 and CD59 are related to herceptin-induced complement-dependent cytotoxicity (CDC), and also promote suppressed anti-tumor effectiveness of herceptin, suggesting that CD55 and CD59 may be useful markers for predicting the clinical response to Herceptin therapy." (PMID 22634835, 2012). "However, complement deficiencies, the over-expression of membrane complement regulatory proteins (e.g. CD55, CD59, and CD46) and fluid phase inhibitors (e.g. CFH, CFHR5, and C4BP) in the tumor microenvironment often cause resistance and non-responsiveness to mAb treatment." (PMID 33193442, 2020).
tumor (continued). "NSE, GRP78, CD55 and CD59 sometimes increased, but for each patient the response of the non-cancerous prostate sample was weaker than that of the tumour sample." (PMID 30820548, 2019). "In agreement with the cell culture results, we observed weak or close to no expression of CD55 and CD59 on the typical spindle tumor cells in KS tumors." (PMID 25254972, 2014). "However, because CD46, CD55, and CD59 are constitutively expressed in human tissues, nonspecific targeting of these molecules can lead to undesired complement activation outside the tumor." (PMID 35860237, 2022). "Notably, there was no statistical difference in the tumour growth inhibition between the PBS and Dox group, implying that the dosage of Dox (1.2 mg/kg) alone almost did not suppress the tumour growth, but can greatly enhance the antitumour effects of CD55‐TMn in vivo." (PMID 33251723, 2020).
cancer (100 papers, 1992 to 2026). A tumor composed of atypical neoplastic, often pleomorphic cells that invade other tissues. "Among the most significant upregulated genes, we identified 3 different isoforms of CD55 a well-known protein coding gene frequently linked to cancer aggressiveness in many carcinomas." (PMID 31717588, 2019). "Interestingly, for the adhesion G protein-coupled receptor E2 have been shown interaction with CD55 which implicated in cancer progression." (PMID 39457608, 2024). "CD55 encodes a glycoprotein involved in the regulation of the complement cascade, prevention of damage to host cells, and is associated with the progression of various cancers." (PMID 31387199, 2019). "Based on the possible function of CD55 in cancer development, we hypothesized that CD55 genetic variants contribute to the risk of developing NSCLC." (PMID 28008159, 2017). "These cancer cells express high levels of Her2 and of the complement regulator CD55, preventing C3 cleavage by the C3 convertase." (PMID 40370471, 2025). "Studies indicate that ADGRE5 and CD55 are involved in different stages of cancer development, highlighting the potential of ADGRE5 as a therapeutic target in oncology/immuno-oncology." (PMID 40862763, 2025). "Among the interaction partners proposed for ADGRE5, CD55 stands out as an immune system component that is dysregulated in many cancers alongside ADGRE5." (PMID 40862763, 2025). "Regarding the key interaction between T cells and cancer cells, increased expression of ligand-receptor pairs MIF_TNFRSF10D, CD55_ADGRE5, CD226_NECTIN2, CCL3L1_CCR1, and CCL3_CCR1 was observed." (PMID 39986271, 2025). "Third, predicted interaction between CD55 expressed by CAFs, basal cancer cells and monocyte/macrophages and the adhesion G protein-coupled receptor E5 (CD97) gene, ADGRE5, on CD4+ T cells was higher with age." (PMID 41188599, 2025). "Studies on the use of anti-Id Abs as cancer vaccines in colorectal cancer have focused on three major tumor antigens of protein nature: EpCAM, CD55, and CEA." (PMID 41441690, 2025). "ARF6 has been associated with several cell-surface receptors expressed on cancer cells, such as CD147, CD44, CD98, CD55, and CD59." (PMID 40733075, 2025). "In this cohort, CD55 expressed by CAFs, basal cancer cells, and monocyte/macrophages was predicted to interact with CD97 (ADGRE5) on CD4+ T cells, which promotes Treg development." (PMID 39483921, 2024). "In conclusion, CD55 has been shown to promote cancer stem cell characteristics in multiple forms of cancer, highlighting its significance in tumorigenesis and aggressive disease." (PMID 38612911, 2024). "The use of bispecific antibodies in the targeting of CD55 has also recently generated interest in the treatment of cancer." (PMID 38612911, 2024). "Compared to the wealth of anti-CD55 antibodies that have been developed as anti-cancer agents, relatively few pharmacological inhibitors have been investigated." (PMID 38612911, 2024). "CD55 deletion mutants were generated and introduced into cancer cells to identify the nuclear trafficking code, cisplatin sensitivity, and stem cell frequency that were assayed using in vitro and in vivo models." (PMID 38853277, 2024). "Next, we verified that cancer cells with high CD55 expression, such as HeLa, PC-3M, and SiHa cells, were able to bind HLA-C∗07:01-VRIG tetramers." (PMID 38939106, 2024). "Rituximab (CD20) was found to cause resistance of cancer cells due to CD55, so one strategy to block CD55 and improve the efficiency of CDC was with an asymmetric bispecific antibody that binds to CD55 and CD20." (PMID 39125875, 2024). "Our previous studies identified cell surface CD55, a member of the complement regulatory proteins, drives chemoresistance and maintenance of cancer stem cells (CSCs)." (PMID 38853277, 2024).
cancer (continued). "CD55, a decay-accelerating factor, protected cells from complement-mediated attack and was involved in cancer progression through mechanisms like cell survival, angiogenesis, and apoptosis inhibition." (PMID 39704173, 2024). "Despite the vast evidence in the literature supporting the use of anti-CD55 antibodies as anti-cancer agents, very few clinical trials have been completed." (PMID 38612911, 2024). "After confirming the correlation of CD55 and S100A9 in H2030-BrM brain metastases, sorted CD55+ and CD55− cancer cells were subjected to oncosphere assays." (PMID 35411077, 2022). "This evidence indicated that CD55 promoted cancer by regulating complement activation either directly or indirectly." (PMID 36741376, 2022). "In this study, cetuximab inhibited the expression of CD46 and CD59, but stimulated that of CD55, thereby protecting cancer cells from both CDC and ADCC." (PMID 36575233, 2022). "Several studies have examined CD55 as a potential biomarker and therapeutic target, establishing that CD55 is frequently upregulated in various cancer types and can serve as an indicator of cancer progression." (PMID 32842508, 2020). "For instance, CD-55 and CD-59 are crucial complement regulatory proteins elevated in various cancers, while Carcino-embryonic antigen (CEA) is a highly specific cancer biomarker, whose targeted immunotherapies are still in the early clinical trials." (PMID 33344222, 2020). "Either way, it is clear that CD55 is not only present in cancer tissues, but also that it plays an important permissive role in the progression of tumorigenesis." (PMID 31164885, 2019). "Our results demonstrate that DPN can reduce CD55 expression at both mRNA and protein level in A431 cells, implicating its use in activation of complement system to kill cancer cells." (PMID 31611744, 2019). "Future experiments should be performed to investigate the effects of macrophages on CD46 or CD55 expression in cancer cells and the interactions between these complement restriction factors." (PMID 31685825, 2019). "Other cancers that show high expression of CD55 and worse clinical prognoses as a result include prostate cancer, ovarian cancer, AML, CML, ALL, gastric carcinoma, and cervical cancer." (PMID 31164885, 2019). "Elevated levels of CD55 have been documented in a wide range of cancers including lung, colorectal, gastric, breast, and cervical cancers as well as in leukemia." (PMID 30319647, 2018). "Overexpression of the membrane-associated C regulatory proteins (mCRPs) CD46, CD55, and CD59 is another mechanism by which cancer cells can evade undesired C attack due to spontaneous or Ab-induced C activation." (PMID 30319647, 2018). "Although previous efforts identified CD55 as a prognostic marker in several cancers, our data provide mechanistic insight into a bifurcating signaling network that regulates self-renewal via ROR2/JNK signaling and cisplatin resistance via LCK signaling." (PMID 28838952, 2017). "CD55, as one of key membrane-bound complement-regulatory proteins (mCRPs), is crucial for the progression of various cancers." (PMID 28008159, 2017). "The role of noncanonical CD55 signaling in T cell receptor activation has been characterized, but there are limited studies on the intracellular actions of CD55 in cancer." (PMID 28838952, 2017). "The expression CD55 in gastric cancer, colon and breast cancer was significantly greater than in those non-cancer tissues." (PMID 28008159, 2017). "We verified that the CD55+ cell population displays the characteristics of an aggressive cancer, with decreased adhesion facilitating increased motility and invasion, coupled with the ability to survive and form colonies in anchorage-independent conditions." (PMID 27043658, 2016). "Through its epidermal growth factor domain region, CD97 binds to CD55, which affects cancer invasion and metastasis." (PMID 25624904, 2015).
cancer (continued). "Niehans and colleagues described deposition of large amounts of CD55 in stroma surrounding infiltrating (adeno)carcinoma of the breast, colon, kidney, and lung, while normal tissue stroma showed only small, localized deposits." (PMID 25596646, 2015). "This modified molecule (CD55/SC-1) is co-expressed with the wild-type of CD55 on the cancer cell surface." (PMID 18053197, 2007). "It is now increasingly recognized that CD55 plays an important role in cancer." (PMID 40596619, 2025). "The stem cell cluster was identified as the cancer stem cells (CSCs) by upregulating the CSCs markers, such as CD55, ERBB3, KRT8, in the volcano plot based on the differentially expressed genes (DEGs, following the STOmicsDB platform default standards) of the stem cell." (PMID 40822927, 2025). "The anti-cancer vaccine 105AD7 is a human anti-Id mAb that functions similarly to CD55." (PMID 41441690, 2025). "Thus, the exploration of therapeutic strategies targeting CD55 in cancer opens diverse avenues for potential interventions against this critical factor in tumorigenesis and aggressive disease." (PMID 38612911, 2024). "Interestingly, 177Lu-anti-CD55 displays synergistic anti-cancer effects when used in combination with cisplatin, significantly reducing H460 cell viability in vitro and increasing the survival of advanced pleural metastatic mice in vivo." (PMID 38612911, 2024). "Therapeutic effects of CD55 inhibition in cancer have been reported." (PMID 35851954, 2022). "Blocking or downregulating CD55 may be an important step in advancing the efficacy of monoclonal antibody (mAb) immunotherapy for cancer." (PMID 36741376, 2022). "Furthermore, cancer cells evolved mechanisms to adapt to complement surveillance (i.e., by overexpression of negative regulators as CD55." (PMID 34572075, 2021). "In particular, CD55 is highly expressed by cancer-stem cells and cisplatin-resistant cancer cells." (PMID 33802004, 2021). "Upregulation of CD46 and CD55 protects cancer cells from complement-dependent cytotoxicity, and the inhibition of these targets may be used as a strategy to enhance the effect of anticancer antibodies, like trastuzumab in HER2+ BC." (PMID 33007869, 2020). "There might be a differential effect of CD55 between healthy and cancer cells at play here, as CD55 in NSCLC is not only down-regulated, but also sialylated." (PMID 33362763, 2020). "Interestingly, cancer cells produce high levels of complement inhibitors, such as factor H, CD55 and CD46, and therefore therapeutics have to be carefully chosen for disease specific targeting." (PMID 32923410, 2020). "In the current study, we hypothesized that estrogen via ER activation in cSCC cells impacts cancer progression by modulating Cyclin D1 and CD55." (PMID 31611744, 2019). "Taken together the findings are consistent with the conclusion that future immunotherapies should aim to achieve a highly specific and profound activation and deposition of complement as well as to disrupt the synthesis and expression of CD59 and CD55 by the cancer cells." (PMID 17623109, 2007). "In this study, we hypothesized that breaking the symmetry of an antibody improved CDC and that its cancer cell-killing effect was synergistically enhanced by formulating a bispecific antibody targeting CD55, an immune checkpoint inhibitor of the complement cascade in the human immune system." (PMID 37880350, 2023). "This might be due to the protective function of CD46 or CD55 on cancer cells." (PMID 31685825, 2019). "These may illustrate the different role of CD55 in normal cells and cancer cells." (PMID 28008159, 2017). "In cancer, ADGRE5 and CD55 are co-expressed and upregulated in several tumors, with higher expression often correlated to increased disease severity and poor prognosis." (PMID 40862763, 2025).